IL20 (interleukin 20)
Diseases named in the same sentence as IL20 in open-access papers (continued):
Sharing a sentence is not in itself a finding about the gene and the disease.
tumor (continued). "Here, we report that elevated IL-20 levels in tumor tissue correlate with poor overall survival in 72 patients with PDAC." (PMID 32929072, 2020). "Blocking the activity of IFN-α with an antibody attenuated IL-20-induced PD-L1 expression in KPC tumor cells in vitro, indicating that IL-20 mediated PD-L1 upregulation via IFN-α." (PMID 32929072, 2020). "We performed immunohistochemical (IHC) staining to analyze the expression of IL-20 in tumor tissue samples from 72 patients with PDAC." (PMID 32929072, 2020). "To further confirm the critical role of IL-20-mediated signaling (IL-20R1) in tumor growth, we generated IL-20R1-knockdown KPC cells and orthotopically injected these cells into the pancreas of C57BL/6 mice." (PMID 32929072, 2020). "IL-20 was strongly expressed in tumor cells and neoplastic ductal epithelial cells but only lowly expressed by ductal epithelial cells in nontumorous pancreatic tissue." (PMID 32929072, 2020). "Immunofluorescence staining revealed that IL-20 colocalized with F4/80+ macrophages in adipose tissue following tumor inoculation." (PMID 32929072, 2020). "In vivo, IL-20 expression was correlated with increased tumor cell proliferation and tissue fibrosis." (PMID 32929072, 2020). "Targeting IL-20 not only prolongs survival and attenuates PD-L1 expression in both murine models but also inhibits tumor growth and mitigates M2-like polarization in the orthotopic PDAC model." (PMID 32929072, 2020). "In a mouse model of bone metastases, treatment with anti-IL-20 mAb 7E was able to reduce tumor growth, bone colonization, and osteolysis." (PMID 31847214, 2019). "The data indicates anti-IL-20 mAb 7E is able to regulate the bone formation and form the microenvironment harmful to tumor cells." (PMID 29690863, 2018). "We also found that anti-IL-20 monoclonal antibody (mAb) 7E alleviates inflammation in oral cancer and suppresses tumor growth." (PMID 29242565, 2017). "Tumor tissue samples were analyzed the expression of IL-20 and cyclin D1 by using immunohistochemistry staining and quantitative real-time polymerase chain reaction (qRT-PCR) analysis." (PMID 29242565, 2017). "Both the proliferation assay in vitro and tumor growth assay in vivo showed that 7E inhibited cyclin D1-mediated tumor growth, which indicates that IL-20 has an important regulatory role in HCC progression through cyclin D1." (PMID 29242565, 2017). "Our results demonstrated that IL-20 is involved in many phases of tumor progression: tumor proliferation, migration, and angiogenesis." (PMID 29242565, 2017). "IL-20 was highly expressed in human HCC tumor tissue, and cell migration was significantly higher in ML-1 cells treated with IL-20." (PMID 29242565, 2017). "We found that IL-20 was associated with cyclin D1 mRNA expression in patients with HCC and three human HCC cell lines, which indicates that IL-20 was involved in tumor growth in HCC." (PMID 29242565, 2017). "Although IL–24 was reported to be a tumor suppressor, the biological functions of IL–20 and IL–24 are different." (PMID 26440411, 2015). "In general, we found that the entire family of IL-10 cytokines including IL-10, IL-19, IL-20, IL-22 and IL-24 was increased in tumor compared to normal skin." (PMID 23667456, 2013). "For example, IL-20 signaling in tumor or stromal cells can drive the expression of Vascular Endothelial Growth Factor (VEGF), Transforming Growth Factor Beta (TGF-β), and Programmed Death-Ligand 1 (PD-L1), which promote immune evasion, angiogenesis, and a tolerogenic microenvironment." (PMID 40806452, 2025). "The therapeutic effects of anti-IL-20 monoclonal antibody (7E) were evaluated in oral cancer and BC in vivo models, in which 7E alleviated key malignant phenotypic characteristics by inhibiting tumor growth and tumor size." (PMID 40806452, 2025).
tumor (continued). "In addition, the treatment with anti-IL-20 monoclonal antibody 7E in vivo enhanced cell apoptosis in a dose-dependent manner, further confirming IL-20’s involvement in many phases of tumor progression." (PMID 40806452, 2025). "Our research findings suggest that therapies inhibiting the IL-20/IL-22RA1 pathway may potentially mitigate the immunosuppressive effects of monocytes and improve the efficacy of the anti-tumor immune response." (PMID 39450166, 2024). "Therefore, targeting IL-20 is beneficial for reshaping the tumor inflammatory microenvironment, establishing effective immune detection, and providing strong support for therapeutic strategies." (PMID 38699038, 2024). "IL-20 has a tumor growth-promoting effect by inducing programmed cell death protein." (PMID 38258051, 2023). "In addition, IL-20 promoted tumor cell colony formation on agar, and a monoclonal antibody to IL-20 inhibited tumor growth in vivo." (PMID 38258051, 2023). "Thus we stained the 72 tumor tissue samples with an anti-PD-L1 antibody and compared the expression of IL-20 and PD-L1 in these patients." (PMID 32929072, 2020). "The anti-IL-20 antibody significantly prolonged the survival of tumor-bearing mice." (PMID 32929072, 2020). "Inhibition of IL-20 by 7E reduced tumor growth in vivo, which may be attributed to reductions in the autocrine effects of IL-20 within the tumor microenvironment." (PMID 32929072, 2020). "We find that IL-20 blockade by 7E prolongs survival and alleviates pancreatic fibrosis in both mouse models, reduces the expression of the immunosuppressive molecule PD-L1 on tumor cells, inhibits tumor growth, and mitigates TAM infiltration." (PMID 32929072, 2020). "The pro-inflammatory cytokine IL-20 promotes tumor growth in several cancer types." (PMID 32929072, 2020). "Targeting IL-20 could effectively inhibit tumor growth, reduce the M2 polarization of TAMs, and alleviate fibrosis, which are all considered to contribute to unfavorable conditions for PDAC progression." (PMID 32929072, 2020). "The expression of the lipolytic genes ATGL and HSL, however, was not affected by IL-20 in the adipocyte cultures, suggesting that IL-20 may indirectly promote lipolysis via the induction of tumor-derived lipolytic factors, such as TNF-α47." (PMID 32929072, 2020). "IL-20 is also a potent angiogenic factor and promotes tumor metastasis." (PMID 32929072, 2020). "It would be interesting to compare tumor development in animals lacking specific IL-20 cytokines or individual receptor chains to STAT3-deficient animals to elucidate the contribution of single members of the IL-20 cytokine family to tumor formation." (PMID 29967613, 2018). "In clinical specimens, IL-20 was highly expressed in HCC tumor tissue." (PMID 29242565, 2017). "The findings of this study suggest that IL-20 plays a role in the tumor progression of HCC." (PMID 29242565, 2017). "In in vivo assays, the anti-IL-20 mAb 7E attenuated tumor growth in mice injected with ML-1 cells." (PMID 29242565, 2017). "HCC tumor tissue expressed higher levels of IL-20 than did non-tumor tissue." (PMID 29242565, 2017). "Recently, several studies have demonstrated that IL-20 plays a critical role in tumor progression." (PMID 28514748, 2017). "Therefore, IL–20 directly affects tumor migration and progression, and indirectly affects these activities by inducing other mediators." (PMID 26440411, 2015). "In our mouse model, IL–20 was highly expressed in the PC–3 tumor cells." (PMID 26440411, 2015). "Additionally, HY-PDT modulated the tumour microenvironment by altering cytokine profiles, such as by increasing IL-20 and sIL-6R levels, which may enhance antitumor immunity and reduce metastasis." (PMID 39857765, 2025).
tumor (continued). "Given that in PDAC, elevated IL-20 levels correlate with poor prognosis, preclinical studies have demonstrated that neutralization of IL-20 using monoclonal antibodies, such as 7E, inhibits tumor growth, reduces PD-L1 expression, and alleviates cachexia symptoms in mouse models." (PMID 40806452, 2025). "We documented up-regulation in the expression of IFN-γ, IL12p70, IL-18, IL-20, MIF, TNF-α, TSLP, BLC, Eotaxin-1, Eotaxin-2, IP-10, MIP-1a, MIP-3a, FGF-2, MMP-1, TNFRII and TWEAK, which are implicated in the modulation of inflammation, apoptosis, tumor growth, invasion, and angiogenesis." (PMID 38954024, 2024). "Thus the alleviation of fibrosis by IL-20 blockade might overcome this issue to improve the penetration of cytotoxic T cells or other chemotherapeutic drugs to allow killing of tumor cells." (PMID 32929072, 2020). "In addition, IL-20 promotes tumor angiogenesis in several mouse models." (PMID 29690863, 2018). "Therefore, we conclude that IL-20 is pivotal in HCC tumor progression." (PMID 29242565, 2017). "In HCC, blocking IL-20 signaling suppresses HCC cell proliferation and tumor growth in vivo, highlighting the therapeutic potential of IL-20R inhibition in liver cancer." (PMID 40806452, 2025). "The mRNA expressions of the majority of genes, including IL13RA2, IL20 and SAA2, were persistently higher in tumor cells lines than Het-1A cells." (PMID 37430202, 2023). "IL-20 was demonstrated to promote M2 polarization, and elevated IL-20 levels in PDAC tumor tissue correlate with poor overall survival." (PMID 37444617, 2023). "As cytokines have paracrine action and play an important role in the tumor microenvironment, the cytokine-cytokine receptor pathway was analyzed and found that many anti-inflammatory factors (IL1R2, IL1B, and IL20) were decreased." (PMID 34122668, 2021). "We found that the tumor size and tumor weight of 7E-treated mice were still smaller than those of PBS- and mIgG-treated mice, indicating that IL-20 blockade can directly inhibit tumor growth in a T cell-, B cell-, and NK cell-independent manner." (PMID 32929072, 2020). "In this study, we investigate the role of IL-20 in PDAC and evaluate the efficacy of IL-20 blockade by 7E in an orthotopic tumor model and a KPC mouse model." (PMID 32929072, 2020). "In this study, IL-20 was highly expressed in HCC tumor tissue and correlated with tumor stages and overall survival." (PMID 29242565, 2017). "The results demonstrated that IL-20 is involved in the pathogenesis of HCC and 7E significantly inhibited tumor growth." (PMID 29242565, 2017). "In conclusion, we demonstrated that IL-20 played pivotal roles in PDAC and that the anti-IL-20 antibody 7E retarded tumor progression, inhibited fibrosis in the pancreas, downregulated PD-L1 expression, mitigated CAC, and synergized with anti-PD-1 therapy to inhibit tumor growth." (PMID 32929072, 2020). "The highly correlated expression between IL-20 and cyclin D1 also suggests that IL-20 might be a predictive marker of HCC tumor growth." (PMID 29242565, 2017). "IL-20 mRNA expression in HCC tumor tissue was significantly higher than non-HCC tissue in 26 patients." (PMID 29242565, 2017). "IL–20 induced the expression of N-cadherin, STAT3, vimentin, fibronectin, RANKL, cathepsin G, and cathepsin K, all of which are involved in cancer cell migration, EMT, and tumor-induced osteolysis." (PMID 26440411, 2015). "Anti-IL–20 and anti-IL-20R1 mAbs are highly stained on tumor cells, but anti-IL-20R2 and anti-IL-22R1 mAbs are not (arrows) on the representative carcinoma tissues." (PMID 26440411, 2015). "Interestingly, IL-5, IL-7, IL-20, and IL-22, rather than their receptors, have been widely reported to have the ability to predict tumor prognosis." (PMID 34497605, 2021). "Therefore, IL-20 produced by cancer cells promotes tumor progression not only by its direct autocrine effect, but also by nurturing a microenvironment for tumor growth and metastasis." (PMID 29242565, 2017).
tumor (continued). "However, studies are yet to unravel the intracellular signaling triggered by IL-24 directing tumor cells to undergo cell death versus those mediated by IL-19 and IL-20 that do not trigger tumor cell death." (PMID 24377906, 2013). "In brief, these findings imply that IL-20 is sensitive to the tumor microenvironment of HCC, negatively regulates the immune response, participates in HCC growth, and affects tumor aggressiveness." (PMID 38699038, 2024). "IL-20 did not alter the growth of CRC cells, implying that IL-20RA-maintained tumor growth was exerted in a ligand-independent manner." (PMID 34336707, 2021).
cancer (30 papers, 2007 to 2025). A tumor composed of atypical neoplastic, often pleomorphic cells that invade other tissues. "Several studies have demonstrated that IL-20, IL-22, and IL-24 are involved in the regulation of programmed cell death by apoptosis and/or autophagy, widely implicated as physiological barriers to cancer development." (PMID 40806452, 2025). "The correlation analysis revealed that the six signature genes were positively correlated with IL-6 and IL-20 indicating the dysregulation of these genes may hamper the regulation of IL-6 and IL-20 and may cause cancer progression." (PMID 38172584, 2024). "Thus, blocking IL-20 is a promising therapeutic strategy to halt breast tumor growth and bone colonization, in turn, prevent cancer-induced bone loss." (PMID 29690863, 2018). "Several works demonstrated that both IL-20 and IL-20RA expression levels are elevated in different types of preclinical models of cancer cells including BC." (PMID 39941053, 2025). "IL-20 enhanced cancer cell mobility and supported invasion ability by increasing MMP-9 and MMP-12 production in breast and bladder cancer cells." (PMID 40806452, 2025). "This review explores the relationship between IL-20 cytokines and key cancer-related processes, including growth and proliferative advantages, angiogenesis, invasion, metastasis, and TME support." (PMID 40806452, 2025). "IL-19, IL-20, and IL-24 are expressed particularly by TH type 2 cells, which orchestrate protective type 2 immune responses and protective function in some cancers but also contribute to chronic inflammatory diseases." (PMID 40806452, 2025). "Top up-regulated genes related to cancer were: (i) IL-20, CLK1, SORBS2, ERG1, PIM1, SNORD3A for normal FHC cells and (ii) TSLP, BHLHA15, LAMP3, ZNF27B, KRT17, ATF3 for cancerous HT29 cells." (PMID 38033043, 2023). "Other genes include immune responses of T cells in cancer cells, insulin-receptor-related protein (INSRR), MHC II complex HLA-DQB and HLA-DQA, IL-12A, IL-20, glucose transporter 4 (GLUT4), insulinoma-associated protein 1 (INSM1), and insulin receptor (INSR)." (PMID 36769056, 2023). "After using PDT, the secretion of IL-20 significantly increased for cancer cells incubated with 0.5 μM HY and irradiated with 1 J/cm2 (18.67 pg/mL ± 1.75 pg/mL)." (PMID 38258051, 2023). "In cancer, IL-20, which is typically secreted by monocytes, macrophages, and dendritic cells, promotes pro-inflammatory signaling, metastasis, and proliferation." (PMID 34901003, 2021). "Based on this data we decided to elucidate the fate of internalized IL-20/IL-22 receptors in MDA-7/IL-24-stimulated cancer cells." (PMID 31489119, 2019). "Although IL-20 is assumed to be a key cytokine in the pathogenesis of cancer, little is known about the factors involved in its regulation in cancer." (PMID 28514748, 2017). "The proinflammatory cytokine IL-20 has gained attention for its role in cancer biology." (PMID 40806452, 2025). "Previous studies have indicated that IL20 takes part in cancer progression in several tumors." (PMID 37430202, 2023). "Recent studies have also shown the regulation of IL-20 signaling in cancer development." (PMID 36006737, 2022). "Moreover, in PTX-treated mice, IL-20 serum level was increased and this phenomenon paired with IL-20 increase in serum of cancer patients undergoing PTX therapy." (PMID 33613570, 2020). "The data demonstrate that IL-20 masters in regulating of cancer-induced bone osteolysis." (PMID 29690863, 2018). "Our results expand upon the current understanding of the regulatory mechanism of IL-20 in cancer." (PMID 28514748, 2017). "Therefore, we expect that the results of our study will facilitate the development of a new therapeutic strategy for targeting IL-20 expression in various diseases, including cancer." (PMID 28514748, 2017).
cancer (continued). "Future studies with a focus on single members and receptors of the IL-20 cytokine family are required to further understand their relevance for chronic inflammatory diseases, clearance of infectious diseases, and development of cancer in the gastrointestinal tract." (PMID 29967613, 2018). "The 6 up-regulated genes (IL-20, CLK1, SORBS2, ERG1, PIM1, SNORD3A) are involved in cancer development." (PMID 38033043, 2023). "All the most up-regulated genes (IL-20, CLK1, SORBS2, ERG1, PIM1, SNORD3A) are involved in cancer development." (PMID 38033043, 2023). "IL19 can directly influence immune cells, IL20 has a significant effect on skin inflammation, and IL24 can promote apoptosis of different types of cancer." (PMID 35883015, 2022). "Other cytokines like IL-6, IL-19, IL-20, TGF-α, TNF-α, and IL-23 are also known to promote cancer progression." (PMID 34681026, 2021). "We found that IL-20 is able to stimulate the growth, migration, and function as an upstream mediator to enhance MMP-9, MMP-12, cathepsin K, and cathepsin G secretion in cancer cells." (PMID 29690863, 2018). "In addition, IL-20 upregulated PD-L1 expression via IFN-α, which is an upstream regulator of PD-L1 produced by some types of cancer cells." (PMID 32929072, 2020). "Intriguingly, cancer-induced muscle wasting was not prevented by 7E treatment in either model, suggesting that IL-20 contributed to CAC mainly by promoting lipolysis in adipose tissues." (PMID 32929072, 2020). "IL-20 induces the expression of MMP9, MMP-12, RANKL, cathepsin K and cathepsin G in cancer cells." (PMID 29690863, 2018).